RNU6-1237P (RNA, U6 small nuclear 1237, pseudogene)
Gene: Small nuclear RNA gene on chromosome 1 (40,177,843 to 40,177,949, forward strand). Ensembl gene ENSG00000207508.
Homologues: Orthologues: chimpanzee U6 (99% identical), pig U6 (88% identical). Paralogues in human: RNU6-1011P (87% identical), RNU6-1029P (87% identical), RNU6-1124P (87% identical), RNU6-338P (87% identical), RNU6-38P (87% identical), RNU6-44P (87% identical), RNU6-49P (87% identical), RNU6-842P (87% identical), RNU6-1117P (86% identical), RNU6-12P (86% identical), RNU6-13P (86% identical), RNU6-140P (86% identical), and 1288 more.